SNRPG (small nuclear ribonucleoprotein polypeptide G)
Description:
Plays a role in pre-mRNA splicing as a core component of the spliceosomal U1, U2, U4 and U5 small nuclear ribonucleoproteins (snRNPs), the building blocks of the spliceosome. Component of both the pre-catalytic spliceosome B complex and activated spliceosome C complexes. As a component of the minor spliceosome, involved in the splicing of U12-type introns in pre-mRNAs. As part of the U7 snRNP it is involved in histone 3'-end processing.
Synonyms: Sm-G; SmG
Tractability: Small molecule: a structure with a bound ligand is known. PROTAC: ubiquitination databases record sites on it; its protein half-life has been measured.
Gene: Protein-coding gene on chromosome 2 (70,281,362 to 70,293,740, reverse strand). Ensembl gene ENSG00000143977.
Subcellular location: Cytoplasm, cytosol; Nucleus
Subcellular location (Human Protein Atlas): Nucleoplasm
Pathways (Reactome):
Metabolism of RNA: SLBP Dependent Processing of Replication-Dependent Histone Pre-mRNAs; SLBP independent Processing of Histone Pre-mRNAs; mRNA Polyadenylation; mRNA Splicing - Major Pathway; mRNA Splicing - Minor Pathway; snRNP Assembly
Disease: Dengue Virus-Host Interactions; SARS-CoV-2 modulates host translation machinery
Chromatin organization: CHD1 and CHD2 subfamily
Gene expression (Transcription): RNA Polymerase II Transcription Termination
Gene Ontology:
Molecular function: protein binding; RNA binding
Biological process: mRNA splicing, via spliceosome; spliceosomal snRNP assembly; 7-methylguanosine cap hypermethylation; negative regulation of mRNA splicing, via spliceosome; nuclear histone mRNA catabolic process; RNA splicing; spliceosomal complex assembly; spliceosomal tri-snRNP complex assembly; spliceosome conformational change to release U4 (or U4atac) and U1 (or U11); U2-type prespliceosome assembly
Cellular component: catalytic step 2 spliceosome; cytosol; methylosome; nucleus; post-mRNA release spliceosomal complex; post-spliceosomal complex; precatalytic spliceosome; SMN-Sm protein complex; spliceosomal complex; U1 snRNP; U11/U12 snRNP; U12-type catalytic step 2 spliceosome; U12-type precatalytic spliceosome; U12-type spliceosomal complex; U2-type catalytic step 1 spliceosome; U2-type catalytic step 2 spliceosome; U2-type precatalytic spliceosome; U2-type spliceosomal complex; U4 snRNP; U4/U6 x U5 tri-snRNP complex; U7 snRNP; nucleoplasm; P granule; small nuclear ribonucleoprotein complex; spliceosomal tri-snRNP complex; and 7 more
Genetic constraint (gnomAD): Loss-of-function variants: 0 observed, 1.92 expected, observed/expected ratio (o/e) 0, 90% interval 0 to 1.38. That is too few expected variants to judge how well the gene tolerates losing a copy. Missense variants: 3 observed, 15.09 expected, observed/expected ratio (o/e) 0.2, 90% interval 0.09 to 0.51. Synonymous variants: 10 observed, 4.48 expected, observed/expected ratio (o/e) 2.23.
Homologues: Orthologues: rabbit SNRPG (99% identical), rat LOC120100604 (92% identical), tropical clawed frog snrpg (91% identical), zebrafish snrpg (89% identical), Drosophila melanogaster SNRPG (72% identical). Paralogues in human: LSM7 (41% identical).
Diseases named in the same sentence as SNRPG in open-access papers:
SNRPG is named in the same sentence as 14 diseases in open-access papers, as found by Europe PMC text mining. Sharing a sentence is not in itself a finding about the gene and the disease. The quoted sentences say what the papers report.
breast carcinoma (2 papers, 2017 to 2025). "We found that four interacting proteins of SNRPG are also upregulated in Cluster 1 of basal breast cancer patients with respect to Cluster 2: BUD13, CWC15, and SNRNP70 and ZMAT12, forming a cluster of interacting proteins enriched for the U2-type spliceosomal complex." (PMID 40867231, 2025). "We selected four genes (NOP10, OST4, SNRPG, TOMM7) known to be present in EVs from MCF-7 breast cancer cells overexpressing Rab27b-GFP11." (PMID 28577337, 2017).
Alzheimer disease (1 paper, 2022). A progressive, neurodegenerative disease characterized by loss of function and death of nerve cells in several areas of the brain leading to loss of cognitive function such as memory and language. "Interestingly, SNRPD2 and SNRPG were not only major pathogenic genes of Alzheimer’s disease but also bridge genes." (PMID 35356432, 2022).
breast tumors (1 paper, 2023). "In this study, we also observed a significant association between high expression of the small nuclear ribonucleoprotein polypeptide G (SNRPG) gene and improved relapse-free survival in patients with HER2+ early stage breast tumors." (PMID 37469415, 2023).
cognitive decline (1 paper, 2024). "The identification of SNRPG as a key gene in our study highlights the potential importance of RNA processing in the pathogenesis of T2D-related cognitive decline." (PMID 39452046, 2024).
glioma (1 paper, 2022). A benign or malignant brain and spinal cord tumor that arises from glial cells (astrocytes, oligodendrocytes, ependymal cells).
lung carcinoma (1 paper, 2025). "Similarly, we identified several splicing proteins, such as SNRPD2, SNRPG, SNRPD3, HNRNPM, HNRNPH3, and SRSF10, in human breast and lung cancer TuNEPs but not in NETs." (PMID 40751052, 2025).
myxofibrosarcoma (1 paper, 2021). A malignant fibroblastic neoplasm arising from the soft tissue. "A highly variable number of DMRs were identified in Myxofibrosarcomas, which were not shared across the sets and included the following genes: MEST (chr 7), C14MC microRNA cluster (also known as miR-379–656; chr 14), SNRPG and FAM136A (both in chr 2) and CCND2 (chr 12)." (PMID 33436720, 2021).
type 2 diabetes (1 paper, 2024). "We found potential genetic biomarkers for MCI in patients with type 2 diabetes using WGCNA combined with the LASSO algorithm and further screened four genes, COX7C, SNRPG, TOMM7, and RPS24, which are associated with the occurrence of type 2 diabetes." (PMID 39452046, 2024). "In addition, we verified that four of these genes (COX7C, SNRPG, TOMM7, and RPS24) are also able to predict the risk of type 2 diabetes and can be used as key genes in type 2 diabetes and MCI." (PMID 39452046, 2024). "The ROC curve was screened by integrating the GEO database, and revealed COX7C, SNRPG, TOMM7, and RPS24 as key genes in the progression of type 2 diabetes." (PMID 39452046, 2024). "The t-test results showed that the expression levels of four genes (COX7C, SNRPG, TOMM7, and RPS24) were significantly different between the type 2 diabetes and control groups (p < 0.05)." (PMID 39452046, 2024).
cancer (6 papers, 2020 to 2025). A tumor composed of atypical neoplastic, often pleomorphic cells that invade other tissues. "The SNRPG gene, encoding small nuclear ribonucleoprotein polypeptide G, was recently found to be related to cancer incidence, but its exact function has yet to be elucidated." (PMID 32296580, 2020). "Future research should include stable knockdown or knockout of SNRPG in animal models to confirm the anti-cancer function and therapeutic potential." (PMID 41016985, 2025). "These divergent roles of SNRPG underscore its functional diversity across various cancer types." (PMID 41016985, 2025). "Proteins like SNRPG, SNRPD2, or even cancer-related are expected to be novel biomarkers to predict for patients with MCI who are more likely to progress to AD." (PMID 34461609, 2021). "These hallmarks were mostly correlated with programmed cell death signaling pathways, suggesting regulation of the cell cycle to promote apoptosis of cancer cells by changing the gene expressions such as knockdown of KIF11 and SNRPG,which is conducive to cancer control for patients of C2 subtype." (PMID 35586564, 2022). "Thus, SNRPG may contribute significantly to the initiation and progression of cancers, and its activity is regulated by both specific and non-specific protein–protein interactions." (PMID 40867231, 2025).
tumor (1 paper, 2021). "SNRPG belongs to the small nuclear ribonucleoprotein peptide family, which might participate in tumor chemotherapeutic resistance." (PMID 34422815, 2021).
SNRPG also shares sentences with these, for which no sentence is quoted: endometrial cancer (1 paper); glioblastoma (1); non-small cell lung carcinoma (1); sarcoma (1).